LGALS3 (galectin 3)
Diseases named in the same sentence as LGALS3 in open-access papers (continued):
Sharing a sentence is not in itself a finding about the gene and the disease.
tumor (continued). "In malignant conditions, Galectin-3 can be produced by tumor cells, but also by stimulated lymphocytes." (PMID 39759523, 2024). "This analysis led to the identification of genes generally associated with cancer cells (MUC1, LGALS3, UGDH, TSTA3, and GALE) or the stromal compartment (LGALS1, PSAP, LGALS9, IDS, and MGAT1) in most of the tumor types analyzed." (PMID 38384845, 2024). "Galectin-3’s role in EMT is evident due to its ability to enhance tumor cell migration and proliferation, contribute to metalloprotease activity in the extracellular matrix, and alter integrin–collagen interactions." (PMID 39451592, 2024). "Glycoprotein VI is thought to bind to galectin-3 (Gal-3) in tumor cells, inducing platelet activation and promoting metastasis in CRC cells." (PMID 38637802, 2024). "In particular, those patients with high FOXP3 expression levels in the tumor compartment and low CD4 levels in the tumor or in the stroma had higher levels of LGALS3 in tumor." (PMID 37567864, 2024). "Studies in galectin-3 knockout mice have shown enhanced tumor-free survival and increased effector T-cell functions, suggesting a role for galectin-3 in immune modulation within the GBM microenvironment." (PMID 38732975, 2024). "We have observed a positive correlation between those patients with high FOXP3+ infiltration in tumor and those with high expression of LGALS3 in tumor (R = 0.6, P = 0.019)." (PMID 37567864, 2024). "LGALS3 (galectin-3) is a galactoside-specific lectin that plays a key role in tumor microenvironment immunosuppression and regulates multiple cellular functions involved in cancer biology and cellular homeostasis." (PMID 39795978, 2024). "The ability of galectin 3 to support cancer cell survival by intracellular and extracellular mechanisms suggests that this molecule is an important component of the tumor microenvironment." (PMID 36718454, 2023). "Previous studies have reported that binding of galectin-3 to TF on the transmembrane mucin protein MUC1 of tumour cells induces tumour cell-cell homotypic aggregation that promotes circulating tumour cell resistance to anoikis in hematogenous dissemination." (PMID 37612278, 2023). "Together, these results suggest that galectin-3-induced protease secretion promotes tumour cell invasion through basement proteins." (PMID 37055381, 2023). "Median Galectin-3 staining scores significantly decreased from benign to adjacent-benign and to tumor tissues." (PMID 36936148, 2023). "Firstly, we verified the expression levels of LGALS3 in LUAD and adjacent non-tumor samples and found that LGALS3 was highly expressed in LUAD samples." (PMID 37265698, 2023). "GPVI is demonstrated to promote colon and breast cancer cell metastasis by enhancing vascular permeability in response to its counter receptor galectin-3 on tumor cells." (PMID 36937386, 2023). "Interaction of Galectin-3 on tumor cells with LAG-3 on CD8+ T cells inhibits anti-tumor immune responses." (PMID 36810098, 2023). "In this regard, it is noteworthy that elegant experiments by Román-Fernández and colleagues have shown PODXL to be a decoy receptor for galectin-3 which modifies its ability to alter integrin-dependent tumor cell invasion." (PMID 38188285, 2023). "LAG-3 is expressed by activated T cells, NK cells, B cells, and DC and binds to the MHC class II (MHC-II) or to the galectin-3 (Gal-3) expressed by tumor cells." (PMID 37046702, 2023). "Overexpression of many galectins, notably galectin-1 and galectin-3, occurs in cancerous cells and correlates with tumor progression and metastasis in some cancers." (PMID 36974238, 2023). "To gain further insight into the influence of C1GalT1 change on tumour cell activities mediated by galectin-3 and MGL, we further analysed the cell surface binding receptors of galectin-3 and MGL in response to change of C1GalT expression in cancer cells." (PMID 37612278, 2023).
tumor (continued). "In OSCC patients, the expressions of galectin-1 and galectin-3 were detected to be significantly higher than in controls, both in blood and in tumor tissues." (PMID 37445908, 2023). "Again, the GPVI-galectin-3 interaction was identified to play a critical regulatory role in platelet–tumor interactions." (PMID 36937386, 2023). "In contrast, the coculture of the tumor cells combined with the selective activation of Vγ9Vδ2 T cells within the PBMC by zoledronate increased galectin-3 release within 72 hours." (PMID 38259448, 2023). "The increased secretion of those proteases by galectin-3 in the tumour microenvironment therefore supports tumour cell invasion through the basement in tumour cell spreading." (PMID 37055381, 2023). "A survey of immune checkpoint receptor ligands revealed upregulation of Lgals3 in fibroblasts, Hmgb1 in tumor cells, and Lgals9 and Cd274 across cell clusters." (PMID 38304252, 2023). "LGALS3 positive samples showed variable and low intensity protein expression (mean positive tumor cells per sample = 35.4%)." (PMID 36745330, 2023). "The present study has also demonstrated that galectin-3-induced protease secretion enhances tumour cell invasion through basement proteins." (PMID 37055381, 2023). "Elevated levels of galectin-3 in cancer cells correlate with immune suppression and progressive tumor stages." (PMID 37685842, 2023). "In our previous study, we used a Proteome Profiler Human XL Oncology Array to analyze the relationships between 84 types of tumor-associated antigens and BAP31, and we found that overexpression of BAP31 increased the expression of galectin-3." (PMID 37762705, 2023). "Dissecting the cellular communications among populations in the tumor revealed that mesenchymal cancer cells in infiltrated tumors communicate through LGALS3 to LAG3 receptor expressed by CD8+ T cells." (PMID 38086828, 2023). "Our previous studies examined the relationship between BAP31 and 84 types of tumor-associated antigens using a Proteome Profiler Human XL Oncology Array, and we found that BAP31 has a positive correlation with galectin-3." (PMID 37762705, 2023). "CD49c/CD29 expressed on endothelial cells is described to bind galectin-3 producing metastatic cells thereby stabilizing tumor/endothelial cell adhesion." (PMID 38259448, 2023). "The daily supplementation of galectin-3 inhibitor TD-139 to three different patients (closed symbols) restored the tumor cell mediated inhibition of Vδ2 T-cell proliferation." (PMID 38259448, 2023). "The results demonstrated that all analyzed tumor cells express galectin-3 and that the coculture with γδ T cells enhanced the galectin-3 release." (PMID 38259448, 2023). "Knockdown of the Galectin-3 by siRNA reduced cell migration, invasion, cell proliferation, anchorage-independent colony formation of the PC-3 cells, and impaired tumor growth." (PMID 36936148, 2023). "Galectin-3 (Gal-3) is overexpressed on the surface of highly aggressive PTC tumor cells and can be a potential target for drug diagnosis and therapy." (PMID 36936158, 2023). "In line with this, in vivo depletion of galectin-3 was shown to increase both the number of functional CD8+ T cells and the consequent expression of pro-inflammatory cytokines, thereby inducing tumor rejection in galectin-3-deficient mice." (PMID 36873388, 2023). "These glycosylation changes reduce galectin-3-mediated tumour cell-cell interaction, cell adhesion and EGFR activation and decrease galectin-3-mediated tumour growth in a chick embryo model." (PMID 37612278, 2023). "Galectin-3 binds TF-antigen and this interaction induces diverse pathological processes such as tumor cell aggregation, cancer metastasis, and T cell apoptosis." (PMID 36873388, 2023). "We also found over-expression of Galectin-3 (Gal-3) and Dectin-1 in the tumor samples compared to the normal samples." (PMID 37910468, 2023). "Galectin-3 also enhances anchorage-independent growth and xenograft tumor growth even after castration." (PMID 36936148, 2023).
tumor (continued). "Galectin-3 is also known to enhance tumour cell adhesion to basement proteins by interaction with cell surface or matrix glycans in cancer progression." (PMID 37612278, 2023). "These suggest that change of C1GalT1 expression in tumour cells can substantially alter tumour cell interaction with galectin-3 and MGL." (PMID 37612278, 2023). "To determine the impact of galectin-3-mediated protease secretion on cancer progression, we assessed the influence of galectin-3-mediated protease secretion on tumour cell invasion through basement proteins." (PMID 37055381, 2023). "In this study, the galectin-3-mediated tumour cell-cell homotypic aggregation and promotion of EGF-induced EGFR activation are seen to be significantly reduced following C1GalT1-suppression." (PMID 37612278, 2023). "The increased cancer cell secretion of cathepsin-B by galectin-3 reported in this study can therefore decrease epithelium integrity and aid tumour cell break up at primary tumour sites." (PMID 37055381, 2023). "LAG3 binds to Galectin-3 (GAL-3) with strong affinity and chronic LAG3 engagement on CD8+ tumor antigen-specific T cells has been implicated in exhaustion of TILs and reduction in their cytolytic capacity." (PMID 38086828, 2023). "Crucially, C1GalT1 suppression significantly reduced galectin-3-mediated tumour cell-cell interaction and galectin-3-promoted tumour cell activities." (PMID 37612278, 2023). "As shown in experimental animal tumor models, targeting the interaction of galectin-3 with N-glycosylated ectodomain MUC16 expressed on serous ovarian cancer cells by high-affinity antibody is suggested as a potential cancer therapeutic strategy." (PMID 38259448, 2023). "In contrast, O-glycan-modifying sialyltransferase ST6GalNAcs reduces the binding affinity of galectins (galectin-1 and galectin-3) to the tumor cell surface, thereby inhibiting intravascular aggregation of tumor cells and consequent metastasis." (PMID 36873388, 2023). "At the early stage of YUMM3.3 tumor growth examined here, Activin-A secretion increased the expression of the ligands Lgals3, Hmgb1, Lgals9, CD274 in various cell types." (PMID 38304252, 2023). "One of the exciting discoveries in this study is the revelation that suppression of C1GalT1 expression reduces the tumour cell interaction mediated by galectin-3 but reciprocally increases their interaction with macrophages mediated by MGL." (PMID 37612278, 2023). "Since an enhanced galectin-3 release is suggested as an intrinsic tumor escape mechanism, we investigated the influence of galectin-3 on the cytotoxicity, proliferation, activation and differentiation of the two major γδ T-cell subsets, Vδ1 and Vδ2 T cells." (PMID 38259448, 2023). "The expression of LGALS3, a siglec-9 ligand in cancer cells, correlates with tumor progression and increased expression of β-catenin and CSC markers induced through Wnt signaling." (PMID 35814473, 2022). "GR-MD-02 is a galectin-3 inhibitor which synergizes with anti-OX40 treatment to promote tumor regression and increases survival of tumor-bearing mice." (PMID 36703969, 2022). "Galectin-1 and galectin-3 assume key roles in stabilizing immune function in addition to playing a critical role in tumor immune evasion." (PMID 36428567, 2022). "This is supported by our previous finding that galectin 3 hampers tumor-reactive T cells in a mixed lymphocyte–tumor culture." (PMID 36249685, 2022). "Among the factors involved in tumor growth, galectin-3 (Gal-3) plays an important role due to its ability to finetune a number of molecular players that act at different levels of cancer-related processes." (PMID 36612048, 2022). "Galectin-3 is overexpressed in cancer cells and the tumor microenvironment, by which an immunosuppressive response is observed." (PMID 36076865, 2022).
tumor (continued). "Galectin-1 and galectin-3 tumors enhance adaptation to the hypoxic microenvironment by promoting angiogenesis, conversion of tumor cell metabolism to glycolysis, and tumor cell adaptation to metabolic stress." (PMID 36428567, 2022). "Modified citrus pectin (commercially named PectaSol-C and GCS-100) has exhibited considerable impact on galectin-3 inhibition, thus reducing metastasis and tumor size and growth." (PMID 36076865, 2022). "Galectin-3 is a structurally unique beta-galactoside-binding protein that has important roles in tumor proliferation and metastasis." (PMID 36428567, 2022). "At the same time, galectin-3 promotes immunosuppressive cells, as Tregs and MDSCs, thus dampening the anti-tumor immune response." (PMID 35682991, 2022). "Galectin-1 and galectin-3 are highly expressed in several tumor tissues, with the former being emerged as a new target for clinical trials." (PMID 36428567, 2022). "Galectin-3 also suppresses tumor cell apoptosis via competing for a conserved structure with Bcl-2, suppressing cyclin, and increasing cell cycle inhibitors." (PMID 35677161, 2022). "We then performed the wound-healing assay for monolayer cells and the 3D migration assay for tumor spheroids, comparing between galectin-3-knockdown and control KKU-213A cells." (PMID 36713574, 2022). "Interaction of immune checkpoint molecules like CTLA-4, LAG-3 or PD-1 with their ligands B7.1/B7.2 on antigen-presenting cells, fibrinogen-like protein-1 and Galectin-3 or PD-L1 on tumor cells, respectively, enhance immune escape of tumor cells." (PMID 36700232, 2022). "In contrast to 2D wound healing, the tumor spheroids of galectin-3-depleted KKU-213A cells revealed ~1.5-fold higher cell migration ability compared to KKU-213A spheroid control (p < 0.01)." (PMID 36713574, 2022). "The other ligands for LAG-3 are LSECtin and Galectin-3 derived from tumor and tumor stromal cells, respectively." (PMID 36077354, 2022). "Galectin-3 is overexpressed in many tumors and positively correlates with the degree of tumor malignancy." (PMID 35677161, 2022). "We found that the RNA expression levels of PDLIM3, PAM, PDLIM7, FSCN1 and LGALS3 were significantly upregulated in tumor samples, which provides ideas for further studies." (PMID 36177006, 2022). "Galectin-1 and galectin-3 make tumor cells prone to homologous aggregation, while CD47 allows tumor cells to escape phagocytosis by immune cells, thus improving tumor cell circulation in vivo." (PMID 36382024, 2022). "This was confirmed in an in vivo tumor model, in which galectin-3 knockdown sensitized tumors to gefitinib to a similar extend as inhibition of dynamin-dependent endocytosis." (PMID 36497271, 2022). "Type-I LacNAc-containing glycans can be utilized to gain novel insights about their functional roles, such as interactions with carbohydrate-binding proteins (e.g., galectin 3), fertilization, pathogen adhesion, and inhibitory activity against tumor cells." (PMID 35281035, 2022). "The investigation of the common 68 proteins in The Human Protein Atlas database (; proteinatlas.org) revealed a similar association between tumor and normal tissues at the protein level for CKAP2L, AURKB, CDC25A, APIP, and LGALS3." (PMID 36529823, 2022). "In tumor cells, galectin-3 has been found to activate Ras/Raf/MEK/ERK signaling, leading to cell survival and pro-survival outcomes." (PMID 36611738, 2022). "During digestion, these fragments bind to and block the activity of the pro-metastatic regulatory protein galectin 3 (Gal-3), inducing tumor progression." (PMID 36364232, 2022). "Galectin-3 plays a crucial role in various processes of carcinogenesis, such as neoplastic cell adhesion, migration, and invasion, as well as contributing to tumor cell survival and resistance to anticancer therapy." (PMID 36432695, 2022). "Galectin-1 and galectin-3 are important contributors to the regulation of immune function and have a unique dual role in tumor regulation." (PMID 36428567, 2022).
tumor (continued). "Western blot analysis indicated that CD47, galectin-1, and galectin-3 were detected on both the biomimetic nanoparticles and tumor cell membrane." (PMID 36382024, 2022). "Galectin-3 is an immunosuppressive molecule in the tumor microenvironment, and it is expressed abundantly in human macrophages and tumor cells under stress, i.e. cytostatic therapy." (PMID 35301393, 2022). "Gal-3, encoded by the LGALS3 gene, is involved in the regulation of tumor cell growth, transformation, apoptosis, immunosuppression, angiogenesis, adhesion, invasion, and metastasis." (PMID 36430322, 2022). "The expression of galectin-1 and galectin-3 on the tumor cell membrane induces homologous aggregation of tumor cells, and it confers biomimetic nanoparticles with tumor targeting ability." (PMID 36382024, 2022). "Galectin-3 is expressed predominantly by activated macrophages and involved in multiple pathological processes, including fibrosis, inflammation, and tumor growth." (PMID 34979958, 2022). "The combination mechanism of MCP and galectin-3 is that the former can recognize galectin-3 on the surface of cancer cells and then inhibit tumor metastasis." (PMID 36432183, 2022). "Overexpression of tumor galectin-1 and galectin-3 were found in 26.8% and 19.5% of patients, respectively." (PMID 35280768, 2022). "Galectin-1 and galectin-3 expression on the tumor cell membrane promotes the aggregation of homotypic tumor cells." (PMID 36382024, 2022). "Galectin-3 has also been shown to exert many modulatory functions in the (tumor) immune microenvironment, e.g., reducing tumor-infiltrating lymphocytes, suppressing T cell activation, and inhibiting the expansion of plasmacytoid DCs." (PMID 36139125, 2022). "All these arguments support the significant role of galectin-3 in reducing tumor infiltration and the killing function of activated T lymphocytes." (PMID 34572756, 2021). "As a control for the used mRNA/RNAseq expression levels, we analysed a second set of 15 UM from Leiden by Fluidigm qPCR, and compared the expression of LAG3, HLA-DR, and Galectin-3 between D3 vs. M3 tumours." (PMID 34503258, 2021). "Galectin-3 expression was also elevated in tumor tissues of humans with ACTH producing Cushing's disease." (PMID 34722704, 2021). "Interaction of TF on mucin protein MUC1 on tumor cells with galectin-3 increases tumor cell–cell homotypic aggregation and promotes tumor cell emboli formation and survival in the circulation." (PMID 34944925, 2021). "Ligands for LAG-3 include MHC-II, Galectin-3 (Gal-3), and liver sinusoidal endothelial cell lectin (LSECtin) expressed by certain tumor types." (PMID 33804419, 2021). "Patients with metastases often have higher circulating galectin-3 concentrations than those with localized tumours." (PMID 34223877, 2021). "Accordingly, several clinical trials are in progress to treat patients with galectin-3 inhibitors and immunotherapy in different tumor types." (PMID 34572756, 2021). "This suggests that circulating PNA mimics the action of circulating galectin-3 by direct interaction with disseminating tumour cells in metastasis promotion." (PMID 34223877, 2021). "Apart from a direct effect on effector T cells, galectin-3 attracts macrophages towards the tumor and promotes their M2 differentiation." (PMID 34572756, 2021). "Such altered glycosylation facilitated the binding of the soluble lectin galectin-3 and resulted in increased tumor cell aggregation, pulmonary tumor cell retention and metastatic burden in vitro or in vivo." (PMID 34975914, 2021). "Second, galectin-3 can inhibit the tumor-reactive T cells and promote tumor growth in the mice receiving the tumor-reactive CD8+ T cells." (PMID 34778306, 2021). "Altogether, these arguments clearly state that galectin-3 plays a central role in tumors escaping the anti-tumor effector function." (PMID 34572756, 2021).